XRCC1 (X-ray repair cross complementing 1)
Diseases named in the same sentence as XRCC1 in open-access papers (continued):
Sharing a sentence is not in itself a finding about the gene and the disease.
cerebellar ataxia (17 papers, 2017 to 2025). A neurological syndrome characterized by clumsy and uncoordinated movement of the limbs, trunk, and cranial muscles. "Another remarkable observation is that human XRCC1 mutations have been linked to cerebellar ataxia and axonal neuropathy, and the resulting marked reduction of XRCC1 protein is coupled to defective SSBR." (PMID 39035020, 2024). "The main symptoms of AOA1/EAOH include cerebellar ataxia, oculomotor ataxia and axonal/sensory neuropathy, which are similar to those of patients with XRCC1 mutation." (PMID 36940705, 2023). "We also evaluated the XRCC1 cancer-associated (P161L, R194W, R280H, R399Q, and Y576S) and the cerebellar ataxia-related (K431N) variants to compare their impact on the ligation efficiency of nick repair intermediate by ligase IIIα." (PMID 34339737, 2021). "For this purpose, we studied the wild-type, the cancer-associated variants (P161L, R194W, R280H, R399Q, Y576S) and the cerebellar ataxia-related (K431N) mutant of XRCC1." (PMID 34339737, 2021). "Intriguingly, we also detected increased PARP1 trapping in primary human fibroblasts from XRCC1-mutated disease, and we reported recently that loss of cerebellar interneurons and cerebellar ataxia in Xrcc1-deleted mice are suppressed greatly by Parp1 deletion." (PMID 34102106, 2021). "For example, the patient with cerebellar ataxia carrying XRCC1 K431N mutation combines phenotypic features of AOA1 and the cells exhibit dramatically reduced repair rates in response to oxidative DNA damage." (PMID 34339737, 2021). "For this purpose, we studied the wild-type XRCC1, polβ interaction mutants (V86R, R109A), the cancer-associated (P161L, R194W, R280H, R399Q, Y576S), and the cerebellar ataxia-related (K431N) variants of XRCC1." (PMID 34339737, 2021). "It has been reported that a deficiency of XRCC1 leads to a reduction in APTX accumulation at the sites of DNA damage, and furthermore, XRCC1 mutations have been found to be associated with cerebellar ataxia, ocular motor apraxia, and axonal neuropathy." (PMID 34339737, 2021). "A recent study showed that biallelic mutations in human XRCC1 are associated with ocular motor apraxia, axonal neuropathy, and cerebellar ataxia." (PMID 32630049, 2020). "Crucially, a very recent publication linked together XRCC1 mutation and occurrence of cerebellar ataxia, which is a hallmark of A-T." (PMID 28973444, 2017). "However, we obtained an increase in the amount of ligation products over the time of reaction incubation in the presence of the cancer-associated (P161L, R194W, R280H, R399Q, Y576S) and cerebellar ataxia-related K431N XRCC1 variants." (PMID 34339737, 2021). "Finally, hereditary XRCC1 mutations result in cerebellar ataxia and deletion of XRCC1 in the mouse brain results in cerebellar ataxia, seizures and juvenile mortality." (PMID 34811483, 2021). "Interestingly, the genetic inactivation of Parp1 (poly (ADP) ribose polymerase 1) rescued ADP ribose levels and reduced the loss of cerebellar neurons and ataxia in Xrcc1-defective mice, implying that PARP1 hyperactivation was neurotoxic to cerebellar neurons." (PMID 32630049, 2020). "Nevertheless, new drugs may be required to specifically treat certain disorders that show different pathogenic mechanisms (e.g. XRCC1-dependent ataxias)." (PMID 30991935, 2019). "Importantly, several DNA-end processing enzymes recruited by XRCC1 are mutated in human ataxias, such as the spinocerebellar ataxia with axonal neuropathy-1 (SCAN1; mutated in TDP1), ataxia oculomotor apraxia-1 (AOA1; mutated in aprataxin) and ataxia oculomotor apraxia-4 (AOA4; mutated in PNKP)." (PMID 30991935, 2019). "Ataxia telangiectasia, AOA1, AOA2, AOA4, XRCC1-AOA, and spinocerebellar ataxia with axonal neuropathy 1 are all caused by genes with a role in DNA repair." (PMID 35326432, 2022).
cerebellar ataxia (continued). "Finally, we demonstrated slight differences in stable polβ/XRCC1 complex formation, polβ and ligase IIIα protein interaction kinetics, and handoff process as a result of cancer-associated (P161L, R194W, R280H, R399Q, Y576S) and cerebellar ataxia-related (K431N) XRCC1 variants." (PMID 34339737, 2021). "Similarly, we observed wild-type level of polβ interaction kinetics with XRCC1 cerebellar ataxia-related mutant K431N." (PMID 34339737, 2021). "Mutations in multiple DNA replication and repair genes such as TCD1, PNKP, XRCC1, and APTX result in ataxia, highlighting the central role of this pathway in these overlapping disorders." (PMID 31230722, 2019). "The hyper-recombination as well as the cerebellar ataxia phenotype in Xrcc1 knockout mice is rescued by Parp1 gene deletion but not by enzymatic inhibition of PARP1." (PMID 30991935, 2019).
pancreatic cancer (16 papers, 2011 to 2025). "The XRCC1 399Gln allele is a potentially important determinant of susceptibility to smoking-induced pancreatic cancer." (PMID 34486486, 2021). "Recently, several studies have investigated the association between SNPs in XRCC1 gene and pancreatic cancer risk." (PMID 29285737, 2019). "The present meta-analysis suggested that Arg280His and c.1517G > C polymorphisms in XRCC1 gene were associated with pancreatic cancer risk." (PMID 29285737, 2019). "In the present study, to obtain a more precise estimation of the association between the XRCC1 gene polymorphisms and pancreatic cancer risk, we conducted a systematic review with meta-analysis by critically reviewing all published studies." (PMID 29285737, 2019). "According to the current evidence-based literature, we thought that there was significant association between XRCC1 gene c.1517G > C polymorphism and pancreatic cancer risk." (PMID 29285737, 2019). "There was significant association between XRCC1 gene c.1517G > C polymorphism and pancreatic cancer risk (allelic model, OR 1.252, 95% CI 1.064–1.473, P = 0.007)." (PMID 29285737, 2019). "Odds ratios (ORs) with 95% confidence intervals (CIs) were determined as measures of the strength of association between polymorphisms of XRCC1 and pancreatic cancer risk." (PMID 29285737, 2019). "The aim of our study was to investigate the association between polymorphisms in XRCC1 gene and pancreatic cancer risk." (PMID 29285737, 2019). "In conclusion, the present meta-analysis suggested that Arg280His and c.1517G > C polymorphisms in XRCC1 gene were associated with pancreatic cancer risk." (PMID 29285737, 2019). "The increased pancreatic cancer risk in individuals carrying the Arg399 polymorphism of XRCC1 is potentially the result of a reduced cellular capacity to repair mutations that result from oxidative DNA damage." (PMID 25988138, 2015). "In particular, a polymorphism in Arg399 of XRCC1 has been identified in pancreatic cancer studies as a risk factor and predictor of therapeutic response." (PMID 25988138, 2015). "Lastly, lack of available data prevented us from performing additional subgroup analyses by age, gender, alcohol consumption and other risk factors, which could be potential factors influencing the evaluation of the associations between SNPs in XRCC1 gene and pancreatic cancer risk." (PMID 29285737, 2019). "Thus, the XRCC1 Arg399 polymorphism, in combination with environmental factors, could potentially be used to identify high-risk individuals for early pancreatic cancer screening." (PMID 25988138, 2015). "Although the underlying mechanisms remain to be fully elucidated in pancreatic cancer models, research has proved that ApoE, DCBLD1 and XRCC1 are significant factors in pancreatic cancer." (PMID 41007358, 2025). "XRCC1 polymorphisms can similarly be applied in PDA to predict response to platinum-based drugs and to identify individuals with increased risk of pancreatic cancer incidence." (PMID 25988138, 2015). "The interaction suggests that XRCC1 Arg399Gln and BER capacity are important in susceptibility to smoking-induced pancreatic cancer." (PMID 21071884, 2011). "For XRCC1 gene Arg399Gln polymorphism, we found no strong evidence of association with susceptibility to pancreatic cancer." (PMID 29285737, 2019). "However, the role of XRCC1 in tumors is contradictory; low expression levels of XRCC1 were observed in gastric and pancreatic cancer and were related to invasiveness, but a high expression of XRCC1 was observed in head and neck squamous cell carcinoma and was related to a worse patient prognosis." (PMID 29312615, 2017). "Summary of APE1, XRCC1, and PARP1 studies in pancreatic cancer." (PMID 25988138, 2015). "Interestingly, PRRX1 could transcriptionally maintain the expressions of DDR genes including ATM, ATR, BRCA1, PRKDC, and XRCC1, in PANC1 pancreatic cancer cells." (PMID 40114375, 2025).
thyroid cancer (15 papers, 2013 to 2024). "More well-designed trials are needed, taking into account ethnic and environmental differences, to better understand the impact of XRCC1 polymorphisms on the development of thyroid cancer." (PMID 38892180, 2024). "The results of a meta-analysis strongly implicate XRCC1 (X-Ray Repair Cross Complementing 1) in cancer development, especially rs1799782 and its association with thyroid cancer." (PMID 32648197, 2021). "First, a meta-analysis of the association of XRCC1 Arg399Gln, Arg280His, and Arg194Trp polymorphisms with thyroid cancer risk is statistically more powerful than any single study." (PMID 25211472, 2014). "A number of epidemiological studies have evaluated the association between XRCC1 Arg399Gln, Arg194Trp, and Arg280His polymorphisms and thyroid cancer risk, but the results remain inconclusive." (PMID 25211472, 2014). "The previous published data on the association between the X-ray repair cross-conplementation group 1 (XRCC1) polymorphisms and thyroid cancer risk remained controversial." (PMID 25211472, 2014). "To clarify the effect of XRCC1 polymorphisms (Arg399Gln, Arg280His, and Arg194Trp) on thyroid cancer risk, we carried out a meta-analysis of all eligible case-control studies." (PMID 23717668, 2013). "This meta-analysis was performed to derive a more precise estimation of the relationship between three XRCC1 polymorphisms and thyroid cancer risk." (PMID 23717668, 2013). "In other words, this is the first meta-analysis undertaken so far of the largest and most comprehensive assessment for the relationship between XRCC1 polymorphisms and the susceptibility to thyroid cancer." (PMID 23717668, 2013). "To date, several studies have been conducted to evaluate the association between XRCC1 polymorphisms and thyroid cancer risk in different ethnic populations, but the results remain conflicting rather than conclusive." (PMID 23717668, 2013). "Over the past decade, several epidemiological studies have reported the association regarding XRCC1 polymorphisms and thyroid cancer risk." (PMID 23717668, 2013). "More importantly, many systematic reviews and meta-analyses have addressed the association of XRCC1 polymorphisms with various cancers, but have not evaluated the association between these polymorphisms and thyroid cancer." (PMID 23717668, 2013). "A total of eleven publications were preliminarily retrieved based on the inclusion criteria for risks of thyroid cancer related to the XRCC1 polymorphisms." (PMID 23717668, 2013). "Although we have put considerable effort and resources into testing possible association between XRCC1 polymorphisms and thyroid cancer risk, there are still some limitations in this meta-analysis." (PMID 23717668, 2013). "A review of several different studies conducted in countries such as Iran, Pakistan, Saudi Arabia, China, Korea, the Czech Republic, and Portugal provides valuable information on the relationship between XRCC1 polymorphisms and predisposition to thyroid cancer." (PMID 38892180, 2024). "In addition, attention has been mainly drawn at a meta-analytical level upon the association of XRCC1 polymorphisms at 194, 280, and 399 with thyroid cancer risk." (PMID 25211472, 2014). "However, the previous meta-analyses on XRCC1 Arg194Trp, Arg280His, and Arg399Gln with thyroid cancer risk have shown conflicting conclusions." (PMID 25211472, 2014). "Investigations into the possible association of XRCC1 Arg399Gln, Arg280His, and Arg194Trp polymorphisms with thyroid cancer revealed that hetero- and homozygous XRCC1 Arg399Gln polymorphism coincided with a decreased risk of DTC in the Caucasian population and mixed population." (PMID 24723911, 2014). "Therefore, it is of particular interest to elucidate the utility of XRCC1 haplotypes in predicting the risk of thyroid cancer." (PMID 23717668, 2013). "The most frequently associated genes with thyroid cancer found on PubMed were BAX, XRCC1, XRCC3, XPO5, IL-10, BRAF, RET, and K-RAS." (PMID 37211566, 2023).
thyroid cancer (continued). "We conducted a comprehensive meta-analysis to explore the association of polymorphisms at XRCC1, XRCC2 and XRCC3 genes with susceptibility to thyroid cancer (TC)." (PMID 34319046, 2021). "As an example, the association of polymorphisms in DNA repair genes XRCC1 (rs25487, rs1799782) and XRCC3 (rs861539) with thyroid cancer risk and progression can be considered." (PMID 29178884, 2017). "Moreover, further studies estimating the effect of gene–gene and gene–environment interactions may eventually lead to our better, comprehensive understanding of the association between the XRCC1 Arg399Gln, Arg280His, and Arg194Trp polymorphisms and thyroid cancer risk." (PMID 25211472, 2014). "However, the same study found that the combination of the XRCC1 rs25487 and XRCC3 rs861539 genotypes contributed to an increased risk of thyroid cancer." (PMID 38892180, 2024). "XRCC1 is one of the candidate genes which its variant relationship with thyroid cancer has not been extensively studied." (PMID 25211472, 2014). "The results of our meta-analysis supported the negative association between XRCC1 Arg399Gln, Arg194Trp, and Arg280His polymorphisms and thyroid cancer risk." (PMID 25211472, 2014). "However, the authors did not observe a significant association of the XRCC1 rs1799782, rs25489, and rs25487 polymorphisms with thyroid cancer." (PMID 38892180, 2024). "For example, the TT genotype of the rs1799782 polymorphism in the XRCC1 gene has been associated with an increased risk of thyroid cancer in all analyzed Chinese populations and in the non-Hispanic white population but with a decreased risk in the Pakistani population." (PMID 38892180, 2024). "We revealed two somatic heterozygote variations in XRCC1 and HRAS genes known to implicate thyroid cancer." (PMID 37175943, 2023). "Our WES analysis of the DNA extracted from the malignant thyroid tissue of patient III8 identified somatic heterozygote missense candidate variations in two genes: XRCC1 and HRAS, reported to have a role in thyroid cancer." (PMID 37175943, 2023).
glioblastoma (14 papers, 2013 to 2025). The most malignant astrocytic tumor (WHO grade IV). "X-ray repair cross-complementing protein 1 (XRCC1) K247la increases the interaction with importin α in glioblastoma stem cells (GSCs)." (PMID 40994548, 2025). "Glycolytic reprogramming-induced XRCC1 lactylation induced therapeutic resistance in ALDH1A3-overexpressing glioblastoma." (PMID 41035644, 2025). "In glioblastoma, lactylation of the X-ray Repair Cross Complementing 1 (XRCC1) protein, a key player in DNA repair, enhances its ability to repair DNA damage, thereby contributing to the development of resistance to chemoradiotherapy." (PMID 41179284, 2025). "In glioblastoma stem cells (GSCs), the Kla modification of X-ray repair cross-complementing protein 1 (XRCC1) promotes its binding with importin-α to facilitate its nuclear translocation, thus improving DNA damage repair capacity and radiotherapy resistance." (PMID 41285721, 2025). "In glioblastoma, lactylated X-Ray repair cross complementing 1 (XRCC1) exhibits an increased affinity for importin α, facilitating the nuclear translocation of XRCC1 and subsequently augmenting DNA repair processes to regulate cancer cell growth." (PMID 41007358, 2025). "The accumulation of lactate increases K247la on X-ray repair cross-complementing protein 1 (XRCC1), which enhances DNA repair through its increased nuclear localization, contributing to the therapeutic resistance of glioblastoma stem cells." (PMID 40563450, 2025). "In addition, general screening of candidate genes revealed that increased expression of IRF9 and XRCC1 as genetic biomarkers are predicative of glioblastoma multiform progression." (PMID 30147694, 2018). "Recent studies have found that ALDH1A3 interacted with PKM2 and facilitated PKM2 tetramerization and lactate accumulation, following by inducing the lactylation of X-ray cross complementing protein 1 (XRCC1) at K247 in glioblastoma (GBM)." (PMID 40612109, 2025). "In xenograft and glioblastoma organoid models, D34-919 blocks the ALDH1A3-PKM2 interaction, inhibiting XRCC1 lactylation and overcoming temozolomide and radiotherapeutic resistance in GSCs." (PMID 40994548, 2025). "Non-histones such as X-ray repair cross-complementing 1 (XRCC1) undergo lactylation at the lysine 247 site (K247), which enhances transport to the cell nucleus and strengthens DNA repair capacity, thereby mediating glioblastoma resistance to therapy." (PMID 41247642, 2025).